CRP (C-reactive protein)
Diseases named in the same sentence as CRP in open-access papers (continued):
Sharing a sentence is not in itself a finding about the gene and the disease.
tumor (continued). "WHO PS ≥ 1, tumor stage IV, the presence of active brain metastases, ≥2 metastatic sites, baseline corticosteroid use, ALB < LLN, LDH ≥ ULN, CRP ≥ 2ULN, ALC < 750/mm3, NLR ≥ 5, and TMTV ≥ 80 mL were significantly associated with worse PFS and OS in univariate analysis (p ≤ 0.047)." (PMID 33418936, 2021). "Based on our knowledge, the present study is the first to compare the significance of these proteins in relation to the well-established tumor markers (CEA and CA19-9) and the marker of inflammation—C-reactive protein (CRP)— in the diagnosis and progression of GC." (PMID 34680333, 2021). "In the present study, we therefore evaluated the potential role of CA19-9, CEA, CRP and other routinely measured laboratory parameters in a large cohort of 125 CRLM patients, who underwent surgical tumor resection with curative intent at our university hospital between 2011 and 2017." (PMID 34829346, 2021). "Considering the controversial aspects of cholesterol-dependent tumor metastasis promotion and the persistently increased levels of LDL and CRP obtained in DTC patients, further research on novel biochemical screening biomarkers and medical target discoveries would provide many beneficial outcomes." (PMID 34429481, 2021). "The included inflammation indexes (such as the NLR, MLR, PLR, SII, and SIRI) and AFP, which were derived from peripheral blood counts (e.g., neutrophil, lymphocyte, and platelet) and acute-phase proteins [e.g., C-reactive protein (CRP) and albumin], represented enabling tumor characteristics." (PMID 34869272, 2021). "We found higher hazard ratios (HR) in non-survivors for the following: respiratory syndromes, shock, respiratory rate, neoplasm, elevated liver enzymes (alkaline phosphatase [ALK-P], alanine aminotransferase [ALT], and aspartate aminotransferase [AST]), LDH, CRP, and the usage of vasopressors." (PMID 34827066, 2021). "C-reactive protein (CRP) is a non-specific indicator of acute inflammation and has been correlated with poor prognosis, likely due to the presence of neutrophils and tumour suppressive cytokines." (PMID 33451015, 2021). "The kinetics of tumor growth is similar in LMC and CRP Tg mice inoculated with B16-OVA cells." (PMID 32709894, 2020). "C-reactive protein (CRP) and Platelet lymphocyte ratio (PLR) could be considered as tumor markers for low-AFP HCC patients, and possess parameter values for tumor growth and invasiveness." (PMID 32518728, 2020). "Serum concentrations of both specific receptors for chemokines (CXCR4, p < 0.001 and CXCR2, p = 0.01) as well as the classical tumor marker (CEA, p < 0.001) and the marker of inflammation (CRP, p < 0.001) were statistically significantly higher in PC patients when compared to healthy volunteers." (PMID 32867211, 2020). "In addition, CRP induces E-selectin and vascular cell adhesion molecule (VCAM) expression, which are key players in the mediation of tumor cell adhesion to endothelial cells and transendothelial migration." (PMID 33023215, 2020). "Because of the small data set of round cell neoplasms, no further statistics were applied to investigate CRP values depending on the tissue origin of the type of neoplasia." (PMID 32434519, 2020). "Correlation between chromogranins and inflammatory parameters (high sensitivity C reactive protein, interleukin-6, and white blood cell count) showed that CgA was not correlated with these parameters in any of the tumor groups (p ≥ 0.0824)." (PMID 33383764, 2020). "This yielded the following point distribution for a new score, which we called the “ACKT” score, ranging from 0 to 7: age > 75 years (1 point); preoperative C-reactive protein (CRP) value ≥ 3 (1 point); preoperative KPS ≤ 70% (2 points); tumor size > 7 cm (3 points)." (PMID 33396290, 2020).
tumor (continued). "When we considered the association between serum concentrations of the analyzed proteins and PC tumor stage according to TNM classification, we found that the serum levels of CXCR4, CRP and CEA were higher in advanced stage of disease in comparison to early PC." (PMID 32867211, 2020). "For instance, the CRP arrest cell-cycle at the sub G1 phase by negatively regulating the PI3K/AKT/mTOR signaling pathway in myeloid leukemia and tongue squamous cell carcinoma thus promoting tumor progression." (PMID 33013829, 2020). "There was a negative but not significant relationship between CRP and tumor epithelial and tumor stromal infiltration of all other immune cells analyzed by the Vectra palette." (PMID 32316975, 2020). "Moreover, using diagnostic criteria, we assessed the diagnostic usefulness of this chemokine in relation to the classical tumor marker CEA and a marker of inflammation C-reactive protein (CRP)." (PMID 32192002, 2020). "Here we investigated the molecular characteristics of tumor tissue and its immune microenvironment in resectable never-smoker LC patients with high and low plasma CRP levels." (PMID 32646072, 2020). "Alb, CRP, NLR, and LMR metrics were significantly different according to tumor histology." (PMID 33137158, 2020). "In order to verify whether CRP and tumor markers were significantly increased in patients with EOC, we measured CRP, CA125, and HE4 concentrations in the blood of 91 patients with EOC and 81 controls." (PMID 33208875, 2020). "High CRP level was a significant negative predictor of OS, independent of Child-Pugh score and existing tumor factors." (PMID 33351844, 2020). "Notably, as albumin / CRP ratio was significant associated with other parameters, we therefore performed subgroup analysis according to tumor size, TNM stage, treatment exposure, serum AFP level, and platelet / CRP (platelet to CRP ratio)." (PMID 31164099, 2019). "According to our knowledge, the present study is the first to indicate the diagnostic usefulness of CXCL-8 levels in the sera of patients with OC in comparison with the classical tumor markers (CEA and SCC-Ag) and the well-established marker of inflammation—C-reactive protein (CRP)." (PMID 30820705, 2019). "Tumors in all cases were FDG-PET positive without an increase in WBC count, CRP value, and tumor marker values." (PMID 31338615, 2019). "Third, several other inflammatory markers related to tumor progression, such as interleukin-6, C-reactive protein, and hypersensitive C-reactive protein, were not included in this study." (PMID 31750248, 2019). "A working hypothesis that we have tested here, is that each or any of CRP, PLR or NLR might be related to indices of tumour aggressiveness, namely MTD, AFP, PVT and multifocality, as an explanation of their prognostic ability." (PMID 30662766, 2019). "We evaluated the local tumor environment, including tumor-infiltrating lymphocytes (TILs), intratumor budding (ITB), and the systemic inflammatory environment, including the neutrophil-to-lymphocyte ratio (NLR) and C-reactive protein (CRP) level." (PMID 30867256, 2019). "For manifest malignant disease, inflammation based scores using more classic inflammatory markers as CRP or albumin indeed have been shown to have prognostic value, independent of tumour entity or stage." (PMID 31463975, 2019). "Concentrations of the classical tumor markers (CEA and SCC-ag) as well as CRP were also found to be higher in OC patients in comparison with the control group, although only CRP (p < 0.001) and SCC-Ag (p < 0.001) levels were demonstrated to be of statistical significance." (PMID 30820705, 2019). "Extra‐abdominal site, localized disease, no effusion or ascites only, absence of thrombosis, normal CRP, complete tumor resection, and chemotherapy with VAIA correlated with EFS in univariate analysis." (PMID 30652419, 2019). "They found that peripheral lymphocyte count (but not serum CRP level) was the strongest indicator of tumor response to CRT." (PMID 30974894, 2019).
tumor (continued). "These analyses revealed that preoperative Kisspeptin concentrations do not correlate with markers of systemic inflammation (leukocyte count and CRP), liver function (AST, ALT, ALP, GGT, and bilirubin), PDAC tumor markers (CEA, CA19-9), or other standard laboratory parameters (supplementary )." (PMID 31772690, 2019). "The results of our analysis showed that the PNI value correlated significantly with lymphocyte count (p < 0.0001), tumor size (p = 0.0327), depth of tumor (p < 0.0001), TNM pStage (p = 0.0005), SCC antigen level (p = 0.0072), albumin level (p < 0.0001), and CRP level (p = 0.0012)." (PMID 29290069, 2018). "Simultaneously, some tumor cells, including ESCC and NSCLC, also have the ability to secret CRP alone and may contribute to the serum CRP level." (PMID 29568406, 2018). "We have found that CRP serum level in patients with CRC was significantly higher with increasing stage of this disease, as well as with increasing of tumor bowel wall infiltration and regional lymph nodes invasion, reaching the highest values in the IV stage CRC." (PMID 30154846, 2018). "IL-6, CRP, and MMP-9 serum levels showed very similar trends, increasing concomitantly and reaching the highest values in stage IV CRC, indicating they are involved in tumor promotion and proliferation." (PMID 30154846, 2018). "In order to liken the environment of a potential micrometastasis site, the tumor cells were cultured on top of a fibroblast monolayer in the presence of PBMCs with or without the augmented levels of CRP and IL-6 observed previously in patient sera." (PMID 30450100, 2018). "The Mann–Whitney U‐test revealed significant intergroup differences in age; maximum tumor size (cm); PNI; the serum levels of albumin (g/dL), CA19‐9 (U/mL), CEA (ng/mL), CRP (mg/dL), and globulin (g/dL); survival period (day); and white blood cell count (×103/mm3)." (PMID 30238078, 2018). "Laboratory data, including results for blood cell count, platelet count, renal and liver function, C-reactive protein (CRP), procalcitonin, urinalysis, and stool routine and tumor markers, were all normal, except that CEA was 9.0 ng/ml, higher than the previous measurement." (PMID 30384858, 2018). "Based on these results, we next evaluated the sensitivity, specificity, and positive as well as negative predictive value (PPV and NPV) of elevated CRP serum levels to predict tumor recurrence." (PMID 28514756, 2017). "Univariate analysis of CRP, NLR and tumor size using log-rank test." (PMID 28727824, 2017). "Cytokines released from tumor and stromal cells upon AT1R activation by AngII include TGF-β, IL-1a, IL-1β, IL-6, IL-8, MCP-1 (monocyte chemoattractant protein–1), M-CSF, COX-2 (cyclooxygenase-2), and CRP (C-reactive protein)." (PMID 28978752, 2017). "Patients with distant tumor recurrence showed higher but not significantly different CRP concentrations compared to those with regional and local recurrences (5.7 ± 2.3 mg/dL compared to 3.12 ± 2.9 mg/dL and 3.05 ± 0.5 mg/dL, respectively; p = 0.764)." (PMID 28514756, 2017). "In contrast, primary tumor site, the response rate, CRP were not different between high and low NLR groups (p =0.162, p =0.214, p = 0.683)." (PMID 27911876, 2017). "Univariate analyses revealed that an increase in the IL-6 level was associated with low levels of albumin (<4.0 g/dL), high serum CRP (≥0.5 mg/L), high serum CEA (≥5.0 ng/dL), high serum CA19-9 (≥37 ng/dL), venous invasion, tumor depth of pT4 disease, distant metastasis, and colorectal obstruction." (PMID 26858756, 2016). "CRP is a nonspecific but sensitive marker of the acute phase response and is expressed in selected tumor cells." (PMID 26880857, 2016). "Thus, both the increasing of C-reactive Protein (CRP) and interleukins and albumin decreasing should be correlated to the advanced tumor stage and poor prognosis." (PMID 27036213, 2016).
tumor (continued). "Immune system promotes tumour vessel regeneration, migration, invasion, and metastasis by raising regulatory T lymphocytes and activation of related modulators such as IL-6 and TNF-α, C reactive protein, induction of neutrophilia, battering down immune system." (PMID 27732958, 2016). "Cytokine intensity was not correlated with PFSR (P = 0.241) but tumor stage was the only independent predictor for 3‐year PFSR in patients with CRP ≥ 5 mg/L in both univariate and multivariate analyses." (PMID 26799163, 2016). "The laboratory evaluation was negative except for a mildly elevated CRP with no tumor markers identified and the spinal tap was positive for elevated protein and particularly oligoclonal bands." (PMID 27335712, 2016). "Furthermore, the multivariate analysis revealed that in addition to tumor stage, cytokine intensity independently predicts PFSR of patients with CRP <5." (PMID 26799163, 2016). "The serum concentrations of CXCL12 and CXCR4 and classical tumor markers such as carcinoembryonal antigen (CEA) and squamous cell cancer antigen (SCC-Ag) were measured using immunoenzyme assays, while C-reactive protein (CRP) levels were assessed by immunoturbidimetric method." (PMID 27041792, 2016). "According to our own observations, however, the intensity of CRP/SAA staining is not as relevant as the uniform pattern of CRP/SAA labeling among tumor cells." (PMID 26404250, 2015). "Our results showed that elevated CRP was an independent prognostic marker in urological cancers, regardless of the tumor type, ethnicity background and cutoff value in the studies." (PMID 26235332, 2015). "On POD 7, Hb, CRP, γ-GTP, and depth of tumor invasion were effective variables." (PMID 26530188, 2015). "CRP seems to represent biologically aggressive tumors with impaired prognosis independent of tumor stage and tumor aggressiveness (tumor differentiation)." (PMID 26248232, 2015). "Interestingly, our data on exosomal protein profiles from treated Caco-2 showed an enrichment of upregulated proteins involved in tumor etiopathogenesis, including CRC (CD59, CRP, CTSD, HMMR, LY6K, TRIM22), and in cell cycle control (BRAF, CDC2, ERBB2)." (PMID 25594007, 2014). "The data revealed good correlations between all the measured serum tumor markers (i.e., TK, B2m, LD, and CRP) and MTVwb or MTBwb regardless of disease types (p<0.01; respectively)." (PMID 24454777, 2014). "In this context, our findings reinforce the observed lack of strong correlations between CRP level in peripheral blood and well-known prognostic markers of inflammation, immune response and proliferation in the local tumor tissue environment." (PMID 25340395, 2014). "A significantly elevated CRP level (>15 vs. ≤ 15 mg/l) was found more often in patients with an advanced tumor stage (≥pT2) (38.9 vs. 11.6%, p=0.007) and in those with nodal disease at diagnosis (50.0 vs. 14.6%, p=0.007)." (PMID 23642165, 2013). "In the univariate analysis, several factors evaluated at one month after SIRT showed prognostic impact concerning overall survival including the tumor response for Choi criteria, the number of nodules, MELD score, and the serum levels of bilirubin, INR, and CRP." (PMID 24367506, 2013). "We also demonstrated that elevated blood CRP and WBC were associated with short recurrence free interval (RFS) and overall survival but tumour-associated neutrophils and macrophages were not directly correlated with RFS or overall survival." (PMID 23945200, 2013). "In this study, we specifically investigated the prognostic predictors in a cohort of HCC patients at one month after treatment with SIRT and established a prognostic scoring model based on the following factors: the tumor response, the number of tumor lesions, MELD score and serum CRP levels." (PMID 24367506, 2013).
tumor (continued). "As biomarkers in body fluids offer the opportunity for more objective and reproducible measurement prior to tumour surgery, the use of CRP as a worldwide well-standardized parameter, should not be underestimated." (PMID 23497335, 2013). "We next examined whether the changes in CRP concentrations or NLR serially measured before and after therapy could predict tumor response." (PMID 23409924, 2013). "The study aimed to evaluate, during colorectal carcinogenesis from benign to malignant phases: i) the trend of serum levels of IL-8, IL-6, TGFβ1, VEGF and MMPs; ii) the parallel trend of CRP serum levels; iii) derangement of the principal TGFβ1 receptors (TGFβ1RI/RII) in tumor tissues." (PMID 22848630, 2012). "The inflammation-based Glasgow Prognostic Score (GPS), based on serum levels of CRP and albumin, has repeatedly been shown to be a predictor of survival, independent of tumor stage, performance status and treatment." (PMID 23092358, 2012). "In addition, a few studies reported that some tumor-based events, such as expression of IL-6 receptor and COX-2 enzyme, or infiltration of T-lymphocytes, are inferior to CRP in determining survival in patients with localized renal cell carcinoma." (PMID 19341447, 2009). "Recently, the systemic inflammatory response in CRC survival, as determined by C-reactive protein (CRP), has provoked interest and may reflect a tumour's malignant potential." (PMID 17242695, 2007). "However, there was an inverse relationship between percentage tumour CD4+ T-lymphocytes and C-reactive protein (P<0.01)." (PMID 15700032, 2005). "Preliminary studies of IgG, IgA, IgM, ceruloplasmin and C-reactive protein suggested that these would not be valuable monitors of tumour burden." (PMID 6158966, 1980). "The superior prognosis observed in the flare group suggests that the CRP flare in this context might represent a more intense and effective anti‐tumor immune activation, rather than a mere inflammatory response." (PMID 41055020, 2026). "Insulin, C-peptide, adiponectin, and C-reactive protein (CRP) were selected to capture participants’ overall insulin sensitivity and inflammation profiles before and after the intervention, and serum PSA changes were investigated as a marker of tumor progression." (PMID 41546786, 2026). "Six samples had acinar and tumor staining with few macrophages positive in the glands, whereas the other six samples had no staining in the tumor, but an increased number of positive macrophages infiltrated within the glands (CRP median H‐score = 350, range 10–600)." (PMID 37415393, 2025). "CRP, ESR, and fibrinogen all had small regression coefficients (each β close to 0, p > 0.5), indicating that systemic inflammation measures did not contribute additional explanatory power for TNF-α levels beyond what the tumor markers and stage already provided." (PMID 40299527, 2025). "CRP, albumin and most composite inflammation scores, but not dNLR, remained as independent prognostic factors for OS after adjusting for age, CgA, PS, Ki‐67, tumour site and number of previous treatments." (PMID 38477040, 2025). "The observed reduction in CRP, stabilization of VEGF, and increase in IFN-γ levels suggest that rcIL-15 may exert complementary anti-inflammatory and immunostimulatory effects relevant to tumor control." (PMID 40552079, 2025). "CRP decline may thus capture early biological effects on the host environment preceding or independent of measurable tumor burden changes, acting as a pharmacodynamic biomarker rather than a direct predictor of RECIST response." (PMID 41267986, 2025). "Although the prognostic significance of CRP, LVI, PNI, and tumor budding is well documented in the literature, our study sheds light on how these factors are distinctly distributed between URC and MLRC, further identifying shared prognostic indicators for both tumor locations." (PMID 40277783, 2025).